CRP (C-reactive protein)
Diseases named in the same sentence as CRP in open-access papers (continued):
Sharing a sentence is not in itself a finding about the gene and the disease.
infection (continued). "We hypothesize that prior to infection autoantibodies cause mild symptoms, but during acute-phase CRP upregulation causes disease relapse by amplifying IgG-mediated cell destruction." (PMID 33790888, 2021). "We suspect that with the weakening of the inflammatory response, other factors such as infection that cause CRP to rise may become prominent; infection can increase CRP and PCT levels after pancreatectomy." (PMID 33784995, 2021). "Elevated CRP levels (≥10 mg/L) increased the risk of infection to 0.72." (PMID 33499272, 2021). "Notably, the appraised levels of CRP in systemic and CNS-related samples were in the pg/ml range and therefore, not symptomatic of acute inflammatory events or accompanying infections but indicative of an underlying and ongoing inflammation." (PMID 33853634, 2021). "Conversely, patients suffering from IgG-mediated cytolysis may benefit from treatment of underlying infections and therapeutic approaches modulating CRP levels (e.g., 1,6-bis[PC]-hexane)." (PMID 33790888, 2021). "The type of infection focus was associated with the presence of fever and CRP levels." (PMID 33800644, 2021). "Together, these data indicate that CRP controls IL-23 production by human monocytes, and thereby may contribute to shaping immunity during infection, but perhaps also worsen the pathology of IL-23-associated chronic inflammatory disorders." (PMID 34769069, 2021). "Also, there is a lack of information about cytokines, ethnicity, genetic polymorphism, precise dating of the infection onset, and biomarkers like C-reactive protein test." (PMID 34347776, 2021). "CRP is a sensitive biomarker associated with inflammation, infection, and tissue damage." (PMID 33132913, 2020). "The CRP level linked with severe infection is variable between the different diseases." (PMID 33266250, 2020). "One possible explanation for that, is that the increase of C-reactive protein levels, as well as decrease of neutrophil chemotaxis and phagocytosis elicited by ethanol exposure may predispose to infection by periodontal bacteria." (PMID 32730269, 2020). "CRP levels have well-established clinical significance over a very wide dynamic range, from small (less than twofold) increases associated with increased cardiovascular disease risk to increases of more than 100-fold in major infections." (PMID 32253915, 2020). "Furthermore, a rigorous, standardised structured assessment of all cases was carried out to establish the presumed cause of infection, using a consensus-based flowchart taking into account clinical syndrome, CRP, and culture results." (PMID 32813708, 2020). "In identifying an association between higher CRP and a modest increase in the likelihood of progression to intermediate/severe disease, we have demonstrated the potential utility of CRP measured early in the course of infection." (PMID 32063229, 2020). "This higher number of participants recognizing CRP measurements could be associated with the pronounced and/or frequently found CRP alterations during infection or other clinical problems." (PMID 32635232, 2020). "High levels of CRP are observed after trauma, tissue necrosis, infection, surgery and myocardial infarction and are associated with an increased risk of cardiovascular diseases, especially coronary heart disease risk, which is a leading cause of death in adults." (PMID 32443702, 2020). "CRP levels return to preoperative levels within 3 weeks; however, it may be elevated by various causes in addition to postoperative infection because elderly patients with comorbid illnesses frequently undergo TJA." (PMID 33256763, 2020). "Like any therapy CRP lowering might have some untoward effects (e.g. it might increase the risk of infection), nevertheless the time for a placebo-controlled double-blind case-controlled clinical trial of CRP lowering therapy may have finally arrived." (PMID 33633738, 2020).
infection (continued). "Clinically, CRP detection is used to differentiate the infection caused by bacteria from virus." (PMID 32443702, 2020). "It is possibly though that for some infections D-dimer might have an improved diagnostic accuracy compared to other serum parameters such as CRP, which has been shown to be unaltered in some low-grade infections." (PMID 32927683, 2020). "Lymphocytosis and high CRP were associated with symptomatic infection." (PMID 32942705, 2020). "Moreover, the higher circulating level of CRP and pathogenic IgG indicated chronic inflammation and infection was involved in the process of ACS." (PMID 33269101, 2020). "Whether the elevation of CRP is the causative etiology or the sequelae of a multifactorial process linking SARS-CoV2-infection to inflammation, atherogenesis or embolism needs further exploration." (PMID 33101164, 2020). "White blood cell (WBC) and C-reactive protein (CRP) levels may increase due to various causes such as infection and inflammation." (PMID 31547519, 2019). "Therefore, identification of potential predicting risk factors leading to early infection related complications is valuable, in particular the significance the CRP (C-reactive protein)-value is of interest." (PMID 31151433, 2019). "Even if elevated CRP levels are often diagnosed in the clinic, infection is the most common cause." (PMID 31226876, 2019). "Higher hs-CRP levels during pregnancy and in early childhood were associated with higher mother and child BMI, cesarean section, smoking, infections, older siblings, bacterial airway colonization, a higher CRP genetic risk score, lower social circumstances and season of sampling." (PMID 30816254, 2019). "The aim of our present study was to enroll adult patients with common causes of undifferentiated fever in Southeast Asia in order to train and evaluate the diagnostic performance of the IMS for these infections, as well as to compare the diagnostic performance against CRP and PCT." (PMID 30870415, 2019). "All together, the findings of these studies suggest that inflammation, measured by elevated CRP may alter involuntary feeding behavior during an acute or chronic inflammatory state, caused by various acute or chronic diseases, including infections." (PMID 31443557, 2019). "The ability of H. influenzae to vary PCh expression to zero may relate to its ability to cause invasive infection by evading attack by CRP." (PMID 30863393, 2019). "Thus, PCT has the highest value in diagnosing infection and is less susceptible to tumour progression than CRP." (PMID 30976022, 2019). "Furthermore, an ongoing infection is often a cause of confusion and fall in geriatric patients, resulting in high CRP D0 and NLR D0 values." (PMID 30509182, 2018). "Additionally, the Cox regression analysis showed that the use of glycopeptides was the significant prognostic factor for mortality when adjusting for malignancy, healthcare-associated infection, and CRP (Hazard ratio, 2.615; 95% CI, 1.105–6.186, p = 0.029)." (PMID 29378565, 2018). "The elevation of WBC, NT-proBNP, and CRP caused by excessive inflammatory reactions in burn patients may affect their efficiency for prediction of infection." (PMID 30595763, 2018). "Repeated infections during early childhood – a critical period of development for the immune system – would cause multiple spikes in serum IL-6 and CRP, which might programme the immune system for persistent low-grade immune activation." (PMID 29198208, 2018). "We found that diagnostic performance of CRP in our study population was limited by widely overlapping distributions between the three target infections, resulting in reduced utility for inpatient populations where these are the three commonest competing aetiologies." (PMID 30107791, 2018).
infection (continued). "We have carried out a longitudinal study to examine the association between exposures to infections during childhood between 1·5 and 7·5 years and subsequent serum concentrations of inflammatory markers (i.e. IL-6 and CRP) at age 9 years and general intelligence (i.e. IQ) at age 8 years." (PMID 29198208, 2018). "Additional studies are warranted to determine whether rigorous treatment of infection and inflammation that lower CRP levels to a normal level will attenuate the risk of AD for ApoE4 carriers." (PMID 30646251, 2018). "CRP, which belongs to the pentraxin family of proteins, is commonly associated with the acute phase immune response, which is the first line of host defense against infection, injury, or trauma." (PMID 29182557, 2017). "Adjusted logistic regression analysis of our data indicated that infections were not only associated with serum levels of IL-10, but also correlated with splenic volume, leukocyte counts, the percentage of Treg cells, and serum levels of CRP and IFN-γ." (PMID 27682880, 2017). "This led us to investigate whether CRP may respond to mild-moderate infections and/or micronutrient deficiencies experienced by pregnant or lactating women." (PMID 28571565, 2017). "Besides inflammation, infection and other environmental factors, genetic polymorphisms influence the expression of CRP." (PMID 28839172, 2017). "Investigations of these viruses could confirm causative agent of such infections for patients with low and normal serum levels of CRP." (PMID 28451028, 2017). "The findings point to CRP as a potential modulator of either risk or severity of infection." (PMID 27701463, 2016). "Multiple linear regression analysis, adjusted for age, severity of disease (NYHA classification III and IV, low EF, HF with preserved EF), and presence of infection indicated an inverse association relative to hs-CRP and NC (β=−0.196; p=0.03) and PCS (β=−0.005; p=0.01)." (PMID 27759823, 2016). "Therefore, the use of biomarkers of inflammation or infection, such as procalcitonin and C-reactive protein (CRP), has been proposed as a guide in the diagnostic process." (PMID 26772604, 2016). "Third: Greater trust was placed in CRP which was used to determine whether the patient’s infection was caused by bacteria or viruses and seemed to override a negative RADT or was used instead of RADT." (PMID 26141740, 2015). "CRP was used to determine whether the patient’s infection was caused by bacteria or viruses and if the result indicated bacteria antibiotics were prescribed (quotation G)." (PMID 26141740, 2015). "Therefore in this study, we incorporated another APR that is C-reactive protein (CRP) test to minimize the bias that can be caused due to infection and tried to determine the effect of IDA on the iron store of term newborns." (PMID 25734012, 2015). "The American Academy of Orthopaedic Surgeons guidelines for the diagnosis of PJI of the hip and knee recommend risk stratification on the basis of preoperative C-reactive protein and erythrocyte sedimentation rates and selective hip aspiration in patients where infection is suspected or likely." (PMID 26583149, 2015). "In this study, the Group B patients, who had a higher average CRP level that may have been caused by their higher anastomotic leak and infection rates, also required longer periods of postoperative hospitalization." (PMID 26000296, 2015). "In contrast, the older sibling with IRAK-4 deficiency demonstrated raised levels of CRP (192 mg/l; normal < 5 mg/l) and IL-6 (1983 pg/ml; normal < 7 pg/ml), potentially indicating a prolonged infection, a disease course which has also been reported in other IRAK-4-deficient patients with severe IPD." (PMID 24625087, 2014).
infection (continued). "Despite these limitations our study provides support to use serial measurements of CRP after elective colorectal surgery for early identification of patients at risk of developing infections, that is to say even before infection diagnosis, having CRP a lower cost of CRP compared to the PCT." (PMID 25132018, 2014). "Despite the possible decrease in blood cultures among patients in low risk of infection, a combination test would entail a net increase in blood cultures from 45.9% to 63.0% if all patients with either a temperature >38.0°C, a CRP ≥100 mg/L or positive SIRS had blood cultures drawn in the MED." (PMID 25027551, 2014). "After correction for age and sex, the presence of an infection was still positively associated with CRP, sTLR2 and sTLR4: unstandardized coefficients 85 (95% CI 64-106, P < 0.001), 23 (95% CI 12-34, P < 0.001), and 6.2 (95% CI 4.2-8.2, P < 0.001), respectively." (PMID 25406630, 2014). "Noninvasive diagnostic tools used to assess the risk of HCA include measurement of maternal serum CRP levels and leukocyte counts, but these conventional infection markers, when used alone, have poor diagnostic value in distinguishing patients with HCA from those with no placental inflammation." (PMID 25291377, 2014). "Serial salivary CRP screening of the at-risk patient may represent a feasible and safe alternative to frequent serum sampling by alerting the care-giver to a potential infection, inflammatory process, and/or surgical complication in the neonatal population." (PMID 25485262, 2014). "During infection macrophages may be exposed to both CRP and TLR ligands in the form of pathogen-associated or damage-associated molecular patterns (PAMPs or DAMPs)." (PMID 24167754, 2013). "Prior studies have examined the association between CRP levels and infection risk." (PMID 23935961, 2013). "The association between high CRP and leukocyte levels and infection might be explained as an augmented reaction to CPB and infective agents." (PMID 23819455, 2013). "We also observed that serum hypoalbumin (OR = 0.98, 95%CI 0.97–0.99), high counts of WBC (especially, neutrophils, OR = 1.04, 95%CI 1.00–1.08), and high levels of serum CRP (OR = 1.03, 95%CI 1.01–1.04) were associated with increased risk for infection in RA patients." (PMID 22548187, 2012). "A value above five might indicate an increased cardiovascular risk, but could also be an hs-CRP returning to normal low levels after an infection." (PMID 22417460, 2012). "In addition, we have observed that despite its wide use as a diagnostic tool for several acute pediatric infections, CRP testing rarely impacted clinical decision-making." (PMID 22943554, 2012). "• LBP, IL-6 and CRP levels are associated with the severity of infection in children population." (PMID 20158885, 2010). "Low zinc levels were associated with fever or CRP implying that infection and acute phase proteins may have influenced the zinc status of the study children." (PMID 20858275, 2010). "An initial appraisal might suggest that early postoperative infection initially declares itself as a rise in C-reactive protein before overt clinical infection develops, and this infection causes decreased long-term survival." (PMID 19319134, 2009). "The CRP concentration is associated with mortality and organ failure, and it is well known that S. pneumonia consistently causes serious infections, while the range of severity is much broader for infections with E. coli." (PMID 18706087, 2008). "Further studies are needed to decide whether markers of the aging process such as comorbidity and frailty influence the diagnostic value of CRP as a marker of infection, as well as whether the diagnostic performance of CRP is affected by severity of infection." (PMID 18706087, 2008).
infection (continued). "On the fifth postoperative day, CRP greater than 12 mg/l (OR = 25.92; 95% CI: 2.17-332.71; p < 0.01) and IL-6 greater than 25 pg/ml (OR = 15.46; 95% CI: 1.19-230.30; p = 0.03) were the only variables associated with infection." (PMID 17505683, 2007). "However, infection markers, such as CRP, began to sharply rise in the second month, indicating an underlying infection occurred that may have contributed to the subsequent development of ACLF." (PMID 41193418, 2025). "IH lesions, particularly when complicated by ulceration or infection, can trigger systemic inflammatory responses and elevated inflammatory markers; more broadly, inflammation is implicated in IH onset and progression, making CRP a useful indicator of host inflammatory status and IH risk." (PMID 41255770, 2025). "Notably, upon infection with K. pneumoniae, the hyperreactive phenotype of Lkb1-deficient platelets disappeared, and instead, a strong hyporeactive phenotype was observed upon CRP-XL stimulation in both groups." (PMID 40332331, 2025). "Future research could examine risk-prediction models that integrate CRP trends with other variables (such as vital signs, clinical risk scores, or novel biomarkers) to produce a more robust early warning system for postoperative infection." (PMID 41153812, 2025). "This study aims to help clarify how clinicians can interpret CRP changes in the days following lung surgery—distinguishing normal postoperative inflammatory responses from unusual patterns that might warrant further diagnostic work-up for infection." (PMID 41153812, 2025). "However, the ratio of ESR to CRP may offer additional diagnostic value, as it has the potential to distinguish between flare and infection in such patients more effectively than evaluating ESR or CRP levels individually." (PMID 40095875, 2025). "Interestingly, periodontal treatment contributed to a reduction in serum CRP levels in the group with inadequate glycemic control, which is a nonspecific marker of inflammation used to assess the presence of inflammation or infection and to evaluate cardiovascular disease risk." (PMID 40667952, 2025). "This association may be attributed to the fact that elevated CRP reflects systemic or local inflammatory activity, which can exacerbate mucosal injury, predispose to infection, disrupt coagulation, and impede mucosal healing—all pathways that collectively increase the likelihood of rebleeding." (PMID 41585275, 2025). "Besides its association with an inflammatory state, CRP levels are also linked to potential infection, which might warn differential diagnosis during disease progression." (PMID 38361940, 2024). "In addition, previous studies demonstrated that several indicators, icluding the prosthesis-free interval, the mean length of antifungal treatment, patients with CCI ≥ 3, and CRP ≥ 6 mg/dL at the time of diagnosis, were potential risk factors for infection recurrence." (PMID 39152412, 2024). "Notably, these 23 cases exhibited common clinical characteristics, including mucopurulent stools, high fever (temperature ≥ 39°C), elevated blood leukocyte counts, and CRP levels, with exclusion of other potential sources of infection, thereby meeting clinical diagnostic criteria." (PMID 39315855, 2024). "The direction of effect suggests a lower level of CRP during early phases of infection may increase the risk of subsequent complications, a novel finding we will continue to investigate further as the pandemic continues and our samples size tragically continues to increase." (PMID 38662664, 2024). "In our study, while elevated levels of erythrocyte sedimentation rate (ESR) and CRP were observed in patients with infections, the results did not demonstrate the effectiveness of these inflammatory markers in differentiating central fever from fever caused by infections." (PMID 38681106, 2024).